AGMO (alkylglycerol monooxygenase)
Description:
Glyceryl-ether monooxygenase that cleaves the O-alkyl bond of ether lipids. Ether lipids are essential components of brain membranes.
Synonyms: TMEM195; FLJ16237
Tractability: Antibody: UniProt predicts a signal peptide or a membrane-spanning region. PROTAC: its protein half-life has been measured.
Gene: Protein-coding gene on chromosome 7 (15,200,317 to 15,562,017, reverse strand). Ensembl gene ENSG00000187546.
Subcellular location: Endoplasmic reticulum membrane
Subcellular location (Human Protein Atlas): Vesicles
Pathways (Reactome):
Metabolism: Triglyceride biosynthesis
Gene Ontology:
Molecular function: glyceryl-ether monooxygenase activity; iron ion binding; protein binding
Biological process: ether lipid metabolic process; lipid metabolic process; triglyceride biosynthetic process
Cellular component: endoplasmic reticulum; endoplasmic reticulum membrane
Genetic constraint (gnomAD): Loss-of-function variants: 39 observed, 32.62 expected, observed/expected ratio (o/e) 1.2, 90% interval 0.93 to 1.56. The synonymous counts are far from expectation, so gnomAD's model fits this gene poorly and the ratio says little. Missense variants: 444 observed, 319.16 expected, observed/expected ratio (o/e) 1.39, 90% interval 1.29 to 1.5. Synonymous variants: 158 observed, 109.65 expected, observed/expected ratio (o/e) 1.44, 90% interval 1.26 to 1.64.
Homologues: Orthologues: chimpanzee AGMO (96% identical), macaque AGMO (95% identical), dog AGMO (91% identical), pig AGMO (86% identical), rabbit AGMO (84% identical), mouse Agmo (83% identical), rat Agmo (83% identical), tropical clawed frog agmo (64% identical), zebrafish agmo (58% identical), Caenorhabditis elegans agmo-1 (37% identical).
Diseases named in the same sentence as AGMO in open-access papers:
AGMO is named in the same sentence as 20 diseases in open-access papers, as found by Europe PMC text mining. Sharing a sentence is not in itself a finding about the gene and the disease. The quoted sentences say what the papers report.
diabetes (3 papers, 2015 to 2023). "The lack of evidence on the association of polymorphisms of other analysed genes involved in glycaemic regulation (GCK, GCKR, DGKB/AGMO) with the risk of post-transplant diabetes in kidney transplant recipients suggests that they do not play a key role in the development of this type of diabetes." (PMID 37628646, 2023).
type 2 diabetes (3 papers, 2019 to 2021). "A possible role for AGMO was implicated by genetic analyses in a variety of human pathologies such as type 2 diabetes, neurodevelopmental disorders, cancer, and immune defence." (PMID 33530536, 2021). "From human genetic studies, a connection to AGMO function and energy metabolism in type 2 diabetes has been indicated and needs to be further analysed by functional analysis using cellular systems or model organisms for in vivo studies." (PMID 33530536, 2021). "In a meta-analysis of type 2 diabetes from two African populations, we replicated the widely reported association at TCF7L2 (rs7903146) and identified a novel association signal at AGMO (rs73284431) that is distinct from previously reported signals in the region." (PMID 31049640, 2019).
autism (2 papers, 2013 to 2021). Persistent deficits in social interaction and communication and interaction as well as a markedly restricted repertoire of activity and interest as well as repetitive patterns of behavior. "Later, other groups confirmed a correlation of rare copy number variations and mutations within the AGMO locus with autism." (PMID 33530536, 2021). "A rare CNV in the AGMO (TMEM195) gene has been identified with autism in AGRE and NIMH cohorts." (PMID 24007566, 2013). "Already before the gene TMEM195 was assigned to AGMO, a spontaneous copy number variation in the region (then called FLJ16237) was identified, leading to a deletion within exons 2–8 in a patient with autism and was strongly correlated to autism spectrum disorders." (PMID 33530536, 2021).
breast carcinoma (2 papers, 2017 to 2025). "THSD7A is notable for its high expression frequency, whereas the role of AGMO in breast cancer remains insufficiently elucidated in the literature." (PMID 41300329, 2025).
colitis (2 papers, 2021). Inflammation of the colon. "AGMO was also reduced in the epithelium of the colon from mice in which colitis had been induced by dextran sodium sulphate." (PMID 33530536, 2021). "Tetrahydrobiopterin treatment, the essential redox cofactor for AGMO, in dextran sodium sulphate-treated mice was able to reverse the pathological effects of provoked colitis." (PMID 33530536, 2021).
autism spectrum disorder (1 paper, 2021). A spectrum of developmental disorders that includes autism, and Asperger syndrome. "AGMO has also been implicated to play a role in neurodevelopmental disorders such as autism spectrum disorders." (PMID 33530536, 2021).
ichthyosis (1 paper, 2015). Disorders of cornification that are characterized by visible scaling and/or hyperkeratosis of most or all of the skin. "Nevertheless, we note that the products of AGMO catalysis are converted to fatty acids by fatty aldehyde dehydrogenase (FALDH), and that FALDH deficiency in humans results in a combination of skin permeability barrier defects, ichthyosis, and neurological disease known as Sjögren-Larsson syndrome." (PMID 25808955, 2015).
situs inversus (1 paper, 2021). A congenital condition in which there is complete right-to-left reversal of the position of the major thoracic and abdominal organs (that is, they are arranged in a mirror image of the normal positioning). "In this study, sequencing data from 262 individuals with either complete situs solitus or complete situs inversus identified a deletion in exons 1–3 of 13 of the TMEM195/AGMO locus." (PMID 33530536, 2021).
tuberculosis (1 paper, 2021). A chronic, recurrent infection caused by the bacterium Mycobacterium tuberculosis. "This is complemented by genome-wide association studies in humans linking alterations in the AGMO locus with the outcome of leishmania infections or with the course of tuberculosis." (PMID 33530536, 2021).
cancer (4 papers, 2017 to 2022). A tumor composed of atypical neoplastic, often pleomorphic cells that invade other tissues. "Little is also known about the role AGMO may play in cancer, which primarily functions to aid in the synthesis of membrane lipids." (PMID 33889300, 2021).
bacterial infection (2 papers, 2015 to 2024). "Our studies reveal an unexpected in vivo role for AGMO in supporting cuticle stability and sensitivity to bacterial infection, presumably via ether lipid metabolism." (PMID 25808955, 2015).
neurodevelopmental disorder (2 papers, 2021). A behavioral and cognitive disorder with onset during the developmental period that involves impaired or aberrant development of intellectual, motor, or social functions. "Other mutations on both AGMO alleles were reported in two unrelated children with a neurodevelopmental disorder (individual 1: p.Trp130Ter and p.Gly238Cys) (individual 2: p.Gly144Arg and p.Tyr236del)." (PMID 33530536, 2021). "This region includes the AGMO (alkylglycerol monooxygenase) gene, which encodes the only enzyme that cleaves the O-alkyl bond of ether lipids and plays a role in the disabilities and neurodevelopmental disorders in humans." (PMID 34503452, 2021).
tumor (2 papers, 2024 to 2025). "Expression-based clustering of cells for the patient-1 tumor sample resolved two HGSOC cell clusters, with fusion RAPGEF5::AGMO evident in tumor cells largely clustered separately from cells expressing SMG7::CH507-513H4.1 and GS1-279B7.2::GNG4, potentially reflecting tumor heterogeneity." (PMID 40086881, 2025). "Sequencing of the patient-1 tumor sample yielded 497 total cells, with 92 cells (19%) identified as HGSOC cells, from which we identified only four somatic fusion transcripts: SMG7::CH507-513H4.1 (26 cells), RAPGEF5::AGMO (6 cells), NTN1::CDRT15P2 (five cells), and GS1-279B7.2::GNG4 (five cells)." (PMID 40086881, 2025). "Sequencing of the Patient-1 tumor sample yielded 497 total cells, with 92 cells (19%) identified as HGSOC cells, from which we identified only four somatic fusion transcripts: SMG7::CH507–513H4.1 (26 cells), RAPGEF5—AGMO (6 cells), NTN1--CDRT15P2 (5 cells), and GS1–279B7.2--GNG4 (5 cells)." (PMID 38464114, 2024).
infection (1 paper, 2025). The state of being infected such as from the introduction of a foreign agent such as serum, vaccine, antigenic substance or organism. "In this study, we investigated the role of AGMO in lipid mediator biosynthesis in M1- and M2-like BMDMs and responsive mouse tissues, both under healthy conditions and during infection." (PMID 40474257, 2025).
metabolic disease (1 paper, 2021). A congenital disorder (due to inherited enzyme abnormality) or acquired (due to failure of a metabolically important organ) disorder resulting from an abnormal metabolic process. "Although the variants of DGKB/TMEM195 were not studied in terms of AGMO/TMEM195 expression or function, the region is considered as metabolic “risk gene”, and the GWAS suggest that AGMO is involved in human metabolic diseases." (PMID 34062826, 2021).
AGMO also shares sentences with these, for which no sentence is quoted: Obesity (4 papers); neurological disease (2); kidney transplant (1); non-alcoholic fatty liver disease (1); Sjögren-Larsson syndrome (1).